BCL2 (BCL2 apoptosis regulator)
Diseases named in the same sentence as BCL2 in open-access papers (continued):
Sharing a sentence is not in itself a finding about the gene and the disease.
Autoimmunity (17 papers, 2011 to 2025). The occurrence of an immune reaction against the organism's own cells or tissues. "Most studies to date measuring the immune effects from BCL-2 modulation have tested ABT-737 in the context of autoimmunity or transplant tolerance and emphasize the compound’s effects on lymphocytes (T and B cells)." (PMID 28066751, 2016). "Here, we find that T cell-specific over-expression of a Bcl2 BH3 mutant transgene results in T cell-driven multi-organ autoimmunity, strongly suggesting that a defect in thymic deletion is indeed sufficient to cause a breakdown in tolerance." (PMID 25182415, 2014). "Loss of Bim, a Bcl-2 BH3-only protein essential for thymocyte apoptosis, rarely results in autoimmunity on the C57BL/6 background." (PMID 25182415, 2014). "Bcl-2 transgenic mice provided the first experimental evidence that inhibition of apoptosis could lead to autoimmunity." (PMID 37993903, 2023). "However, Treg-specific deletion of Mcl-1 produced lethal autoimmunity as early as 4 weeks of age, a much shorter time frame than the potential role we detected for Bcl-2 in supporting IL-2-dependent Treg survival." (PMID 30833563, 2019). "Thus, our study reveals a previously unrecognized synergism between ETV6/RUNX1 and BCL2 impacting on malignant disease and autoimmunity." (PMID 26919255, 2016). "In BPDCN, BCL2 levels are higher as compared with normal pDCs31, which may indicate that BPDCN cells are comprised long-lived malignant pDCs in patients who are susceptible to autoimmunity." (PMID 31811114, 2019). "However, our results show that Bcl-2 Tg mice may develop autoimmunity at low penetrance, as some mice exhibited a modest accumulation of activated T cells and autoantibodies." (PMID 25182415, 2014). "Consistent with the role of some of these antibodies in autoimmunity, TRAF3/BCL2 double-tg mice also develop autoimmune lesions, such as IgG depositions in glomeruli and tertiary lymphoid organs formation." (PMID 30687320, 2018). "Although we cannot completely rule out this possibility, the fact that Bcl-2 Tg mice do not develop autoimmunity would suggest a minimal role for defective peripheral tolerance in this model." (PMID 25182415, 2014). "Indeed, BCL-2 is not required for Treg survival, as opposed to MCL-1, another member of the BCL-2 pathway, the loss of which leads to fatal autoimmunity in a mouse model." (PMID 38812504, 2024). "Females that had another associated autoimmune condition had an elevated CD69 expression and a decreased BCL2 expression compared with females without an autoimmune condition indicating an activated and exhausted phenotype in chronically affected study participants." (PMID 36741413, 2022). "Differential expression of the BH3 vs wild-type Bcl2 transgenes in the CD8 T cell compartment might also contribute to the development of autoimmunity in BH3 Tg, but not Bcl-2 Tg mice." (PMID 25182415, 2014). "In addition, T-cell specific over-expression of Bcl-2, which can inhibit both Bim and Puma, does not lead to autoimmunity, suggesting that a defect in T cells alone may be insufficient to cause disease." (PMID 25182415, 2014).
brain injury (17 papers, 2013 to 2025). Acute and chronic (see also brain INJURIES, CHRONIC) injuries to the brain, including the cerebral hemispheres, CEREBELLUM, and brain STEM. "Based on GO analysis, miR-16 was involved in a variety of regulatory processes that are triggered by brain injuries, including positive apoptotic regulation via BCL-2 targeting." (PMID 41301762, 2025). "BDNF increases the expression of the antiapoptotic Bcl-2 protein, and thereby exerting part of its neuroprotective effects against brain injuries." (PMID 33936582, 2021). "It suggests that carvacrol blocks TRPM7 function partly by reducing its enzyme substrate, m-calpain, to restore Bcl-2 expression leading to prevention of apoptosis in neonatal hypoxic-ischemic brain injury." (PMID 25761704, 2015). "Treadmill exercise suppressed Bax expression and increased Bcl-2 expression in the hippocampus following traumatic brain injury." (PMID 24520250, 2014). "After brain trauma, Nrf2 translocates to the nucleus, activates expression of genes with neuroprotective function, and thereby leads to upregulation of expressions of various detoxification and anti-cell death factors, such as Bcl-2 and HSP70s." (PMID 38405399, 2024). "The increase in the Bcl-2/Bax ratio and decrease in caspase-8 and −9 levels demonstrated that pre-treatment with SHJKSmex resulted in anti-apoptotic effects in mice with ischaemic brain injury." (PMID 34184969, 2021). "Studies have shown regulated Bcl2 expressions following brain trauma." (PMID 25136963, 2014). "The results are different from our previous work in mouse traumatic brain injury showing that 7,8-DHF administration increased the Bcl-2/Bax ratio at 4 days post-TBI." (PMID 31307481, 2019). "The present study examined kinetics of apoptosis and expression of apoptosis-related proteins Bcl-2, Bax, and caspase-3 in the CA3 hippocampus cells after diffuse brain injury (DBI) induced experimentally in rats." (PMID 23559276, 2013). "While proteins Bcl-2, Bax, and caspase-3 were shown to regulate apoptosis induced by TBI, their expressions and relations to apoptosis after the closed head diffuse brain injury (DBI) have rarely been reported." (PMID 23559276, 2013).
breast adenocarcinoma (17 papers, 2001 to 2025). "Overall these results demonstrate that Bcl-3 is an important regulator of normal mammary gland biology and contributes to the development and/or progression of mammary adenocarcinoma, at least in part, as a consequence Bcl-2 regulation." (PMID 35681213, 2022). "Moreover, they demonstrated in MCF7 (human breast adenocarcinoma) cells high levels of the SAV1 protein but low levels of the BCL-2 protein." (PMID 38136317, 2023). "BA-b-CD induced Bax expression and inhibited Bcl-2 expression to decompose the mitochondrial outer membrane, release cytochrome C, and activate the downstream apoptosis cascade, which inhibited the proliferation of breast adenocarcinoma cells." (PMID 37050126, 2023). "Moreover, VEGF upregulates BCL-2 and inhibits apoptosis in human and murine mammary adenocarcinoma cells." (PMID 23599749, 2013). "Overall these results support a role for Bcl-3 in the regulation of non-canonical and canonical NF-κB activity and Bcl-2 expression in mammary adenocarcinomas such that its absence results in preferential expansion of squamous tumors lacking both NF-κB activity and Bcl-2 expression." (PMID 35681213, 2022).
metastatic disease (17 papers, 1995 to 2025). "A higher median H-Score for BCL2 was noticed in normal tissues compared to primary and metastatic tumors, while high values of BCL2 expression, over 200, were detected only in tumor tissues." (PMID 41514585, 2025). "Yet another study reported significant increase in positive staining for BCL-2 (1% vs. 11%) in metastatic tumors." (PMID 30871232, 2019). "We examined expression profile of Bcl2 in few primary and metastatic tumor BC datasets." (PMID 38223131, 2024). "The analysis reflected that Bcl2 is expressed more in primary as related to metastatic tumors." (PMID 38223131, 2024). "Fisher's exact test confirmed that the metastasis sites were similar in terms of bcl-2 protein expression, survival, and presence of unresected metastatic disease by the end of the study (Fisher's P = 1.0, P = 0.333, and P = 0.429 for lymph node, subcutaneous, and visceral metastases, respectively)." (PMID 18570663, 2008). "However, the mean Bcl-2 expression was significantly lower in patients who developed metastasis during follow-up or died of metastatic disease (P = 0.006 and P = 0.01 respectively)." (PMID 7734290, 1995). "Pro-apoptotic agents 'Oblimersen', an antisense inhibitor of Bcl-2, and 'Sorafenib', an orally active small molecule inhibitor of wild type and mutant BRAF or PLX4032 a potent inhibitor of BRAF with the V600E mutation are at the forefront of novel therapies developed for advanced metastatic disease." (PMID 21682901, 2011). "Simultaneous disruption of both BCL-2 and MCL-1 via small-molecule inhibitors induces robust regression of tumors in a SS PDX model and cell-line xenograft model as well as multiple cell lines derived from both primary and metastatic disease." (PMID 34065859, 2021). "In principle, a combination of a BH3 mimetic, such as BI-97D6 with more pronounced Bcl-2/Mcl-1 inhibitory activity, with a CRCA such as Ad.tCCN1-CTV-m7 expressing a systemically active cytokine, mda-7/IL-24, should elicit profound efficacy toward both primary and metastatic tumors in the clinic." (PMID 25926554, 2015).
preeclampsia (17 papers, 2010 to 2025). Preeclampsia is a hypertensive disorder of pregnancy that is characterized by new-onset hypertension with proteinuria presenting after 20 weeks of gestation, and depending on mild or severe forms may initially present with severe headache, visual disturbances, and hyperreflexia. "In summary, our study identified MKNK1, ARNT, FLT1, SERPINE1, ENO3, LDHA, BCL2 out of HIF1-signaling pathway as novel diagnostic biomarkers for preeclampsia patients, and a diagnostic signature based on these genes is constructed for preeclampsia." (PMID 37020283, 2023). "Seven genes (including MKNK1, ARNT, FLT1, SERPINE1, ENO3, LDHA, BCL2) were screen out to build potential diagnostic model of preeclampsia." (PMID 37020283, 2023). "Secondly, while focused on PDE3A as a key downstream effector of IGF2BP3, we acknowledge the emerging significance of apoptotic and autophagic regulators such as BCL-2 and Beclin-1 in preeclampsia and HELLP syndrome." (PMID 40563987, 2025). "In preeclampsia, increased Bax expression and decreased Bcl-2 have been reported to contribute to elevated apoptosis in placental cells." (PMID 41385535, 2025). "B cell lymphoma 2 (Bcl2) is an antiapoptotic marker which is found lower in preeclampsia placenta than health placenta, while the role BCL2 in preeclampsia needs further research." (PMID 37020283, 2023). "On the other hand, Endo-EVs contained miR-155, which inhibits trophoblast migration and proliferation, increases preeclampsia in patients, and induces trophoblast apoptosis by targeting BCL2 (apoptosis regulator)." (PMID 36231141, 2022). "The increase of syncytial knots in trophoblasts has been observed and associated with down regulation of anti-apoptotic factors of the intrinsic pathway such as BCL2 and Mdm2 and with premature aging of the placenta in preeclampsia." (PMID 32116801, 2020). "This decrease in BCL-2 is consistent with findings in placentas affected by preeclampsia, where a pro-apoptotic environment may contribute to impaired placental function and adverse fetal outcomes." (PMID 40136702, 2025). "FA could also improve placental apoptosis in NG-nitro-l-arginine methyl ester (L-NAME)-induced preeclampsia (PE) rat model through increasing BCL-2 expression and decreasing BAX expression." (PMID 39268468, 2024). "Preeclampsia has been associated with increased markers of apoptosis in trophoblasts/the placenta, and we also observed an increase in the pro-apoptotic BAX/BCL2 ration in pre-term preeclamptic placentae." (PMID 30455461, 2018). "However, the impact of Astragalus on preeclampsia-related symptoms and the Bax, Bcl-2, and caspase-3 in the placental of PE rats remain unclear." (PMID 41385535, 2025).
preeclampsia (continued). "Therefore, the identification of interventional agents targeting the Bax/Bcl-2/caspase-3 pathway may become a new treatment for preeclampsia." (PMID 41385535, 2025). "Additionally, it has been discovered that down-regulation of Annexin7 in placenta of preeclampsia patients inhibits the JAK1/STAT3 pathway in trophoblast cells, leading to a decrease in BCL2 protein levels and induction of cell apoptosis, thus contributing to the development of preeclampsia." (PMID 38235138, 2023). "In the myometrium of the early-onset preeclampsia group OPA1 and Bcl-2 were up-regulated compared to those of the control (p < 0.05)." (PMID 28736722, 2017). "It has been recently demonstrated that berberine hydrochloride could alleviate preeclampsia by regulating IL2/IL10 and BCL2/BAX expressions in preeclampsia rat models." (PMID 29765977, 2018). "Another study showed that reduced BCL2 expression in the placentas of pregnancies with recurrent miscarriage and those with complicated IUGR and preeclampsia led to the increased death of trophoblast cells and may be one of the etiological components of these diseases." (PMID 33803239, 2021). "In placenta from term preeclampsia, we found a decrease in pro-apoptotic BAX and an increase in anti-apoptotic BCL2, as well as no change in CASP9, demonstrating active mitochondrial suppression of apoptotic signalling and suggesting that mitochondria promote cell survival in these placentae." (PMID 30455461, 2018).
rectal cancer (17 papers, 2005 to 2025). A primary or metastatic malignant neoplasm that affects the rectum. "We showed that ki-67 and Bcl-2 expression level were decreased, while Bax was increased in rectal cancer cells after SNHG17 knockdown (p < 0.01)." (PMID 34249085, 2021). "Another study in rectal cancer found that HMGB1 knockdown by RNAi activated caspase-3 and PARP, downregulated Bcl-2 expression and eventually induced apoptosis in rectal cancer cells." (PMID 30157958, 2018). "Bax and bcl-2 expression as predictive markers of response to pRCT was studied in 130 rectal cancers; bax expression was higher in TRG responders than in TRG non-responders." (PMID 24212803, 2011). "Moreover, with regard to tumor location, the Bax/Bcl-2 ratio was found to be significantly lower in colon compared to rectal cancer." (PMID 28253296, 2017).
colorectal adenocarcinoma (16 papers, 1997 to 2024). The most common type of colorectal carcinoma. "Isoangustone A induced apoptosis and activated the caspase cascade cleavage while down-regulated Bcl-2 protein in human colorectal adenocarcinoma (SW480) cells." (PMID 34768743, 2021). "Although the molecular features of CNECs are similar to those observed in colorectal adenocarcinomas, decreased expression of Rb and high expression of p16 and Bcl-2 were more pronounced in CNECs than in colorectal adenocarcinomas." (PMID 29652830, 2018). "MiR-32-5p was significantly decreased in fatty acids-treated human colorectal adenocarcinoma cells accompanied by a decrease in BCL-2 and BCL2L11 expression." (PMID 29225772, 2017). "In the last year, a number of studies have reported the expression of bcl-2 in colorectal adenocarcinomas." (PMID 9020491, 1997). "Recently, Lactobacillus was shown to induce apoptosis of the human colorectal adenocarcinoma cell line HT29 by enhancing pro-apoptotic BAX protein expression and decreasing anti-apoptotic BCL-2 protein expression, leading to the inhibition of cell growth." (PMID 28632155, 2017). "In this study, anti-tumour activity of new SMAC-mimetics Birinapant and AT-406 is evaluated against colorectal adenocarcinoma cells and IAP cross-talk with either oncogenic BRAF or BCL-2, or with the TRAIL are further exploited towards rational combined protocols." (PMID 27520705, 2016). "However, the influence of bcl-2 expression on response to chemotherapy and outcome in patients with advanced colorectal adenocarcinoma has not been reported." (PMID 9020491, 1997).
colorectal tumors (16 papers, 1996 to 2025). "By hierarchical clustering of hub genes using Xena Functional Genomics Explorer, we found that PHLPP2, ACALB, IGF1, and BCL2 were low‐expressed in colorectal tumor tissues." (PMID 33190424, 2021). "To confirm further the results of the in vitro experiments, we used immunofluorescence to detect the expression of P-STAT 3, IL-6, Bcl-2, and Cyclin D1 in colorectal tumors." (PMID 33082817, 2020). "Human colorectal tumors that highly expressed BCL-2 and Ki-67 had a greater tendency towards death within 60 months." (PMID 32102251, 2020). "It has been reported that Bax and Bcl-2 expression is the most predictive outcome when combined as Bax/Bcl-2 expression ratio in colorectal tumors compared to expression levels of the Bax and Bcl-2 genes alone." (PMID 31861952, 2019). "Elevated expression levels of Bcl-2, CyclinD1, COX-2, TGF β1, and F4/80 in colorectal tumors in Min mice were only slightly lowered by OPN deficiency." (PMID 28505114, 2017). "We analysed bcl-2 expression in 231 colorectal tumours from patients that were treated by surgery alone or with 5-fluorouracil-based chemotherapy." (PMID 9020491, 1997). "We suggest that bcl-2 provides a survival advantage in the proliferative compartment of normal crypts and colorectal neoplasms." (PMID 8611422, 1996). "Expression levels of cell survival/growth-related genes, Bcl-2, CyclinD1, COX-2, and transforming growth factor (TGF) β1 were higher in colorectal tumors than those in adjacent colorectal mucosa in Min/OPN(+/+) mice." (PMID 28505114, 2017). "Interestingly, PXN expression was positively correlated with Bcl-2, pBcl-2-S87, and MMP2 expression in colorectal tumors." (PMID 25826088, 2015).